PECAM1 (platelet and endothelial cell adhesion molecule 1)
Description:
Cell adhesion molecule which is required for leukocyte transendothelial migration (TEM) under most inflammatory conditions. Tyr-690 plays a critical role in TEM and is required for efficient trafficking of PECAM1 to and from the lateral border recycling compartment (LBRC) and is also essential for the LBRC membrane to be targeted around migrating leukocytes. Trans-homophilic interaction may play a role in endothelial cell-cell adhesion via cell junctions. Heterophilic interaction with CD177 plays a role in transendothelial migration of neutrophils. Homophilic ligation of PECAM1 prevents macrophage-mediated phagocytosis of neighboring viable leukocytes by transmitting a detachment signal. Promotes macrophage-mediated phagocytosis of apoptotic leukocytes by tethering them to the phagocytic cells; PECAM1-mediated detachment signal appears to be disabled in apoptotic leukocytes. Modulates bradykinin receptor BDKRB2 activation. Regulates bradykinin- and hyperosmotic shock-induced ERK1/2 activation in endothelial cells. Induces susceptibility to atherosclerosis (By similarity). [Isoform Delta15]: Does not protect against apoptosis.
Synonyms: PECAM-1; CD31; CD31/EndoCAM; GPIIA'; PECA1; endoCAM
Tractability: Antibody: UniProt places it where antibodies can reach, with high confidence; its Gene Ontology location is reachable by antibodies, with high confidence; UniProt predicts a signal peptide or a membrane-spanning region. PROTAC: ubiquitination databases record sites on it; its protein half-life has been measured.
Gene: Protein-coding gene on chromosome 17 (64,319,415 to 64,413,776, reverse strand). Ensembl gene ENSG00000261371.
Subcellular location: Cell membrane; Cell membrane (Isoform Long); Membrane raft; Cell junction; Cell junction (Isoform Delta15)
Subcellular location (Human Protein Atlas): Nucleoli; Plasma membrane
Pathways (Reactome):
Hemostasis: Cell surface interactions at the vascular wall; PECAM1 interactions; Platelet degranulation; Platelet sensitization by LDL
Cellular responses to stimuli: High laminar flow shear stress activates signaling by PIEZO1 and PECAM1:CDH5:KDR in endothelial cells
Extracellular matrix organization: Integrin cell surface interactions
Immune System: Neutrophil degranulation
Gene Ontology:
Molecular function: protein binding; protein homodimerization activity; receptor ligand activity; transmembrane signaling receptor activity
Biological process: bicellular tight junction assembly; cell surface receptor signaling pathway; cell-cell adhesion; cellular response to mechanical stimulus; detection of mechanical stimulus; diapedesis; establishment of endothelial barrier; glomerular endothelium development; homophilic cell-cell adhesion; leukocyte cell-cell adhesion; monocyte extravasation; neutrophil extravasation; phagocytosis; positive regulation of cell migration; positive regulation of intracellular signal transduction; positive regulation of MAPK cascade; positive regulation of phosphatidylinositol 3-kinase/protein kinase B signal transduction; positive regulation of protein localization to cell-cell junction; T cell activation; vasodilation; cell recognition; immune response; maintenance of blood-brain barrier; signal transduction; blood vessel development; and 4 more
Cellular component: anchoring junction; cell-cell junction; extracellular exosome; extracellular region; membrane raft; plasma membrane; protein-containing complex; external side of plasma membrane; platelet alpha granule membrane; secretory granule membrane; cell periphery; cell-cell contact zone; cytoplasm; membrane; smooth muscle contractile fiber
Homologues: Orthologues: chimpanzee PECAM1 (92% identical), macaque PECAM1 (90% identical), rabbit PECAM1 (73% identical), dog PECAM1 (72% identical), pig PECAM1 (72% identical), guinea pig PECAM1 (66% identical), rat Pecam1 (65% identical), mouse Pecam1 (63% identical), tropical clawed frog pecam1 (29% identical), zebrafish pecam1a (23% identical), zebrafish pecam1b (22% identical). Paralogues in human: FCRL5 (18% identical), FCRL3 (16% identical), FCRL2 (14% identical), FCRL4 (13% identical), FCRL1 (12% identical), FCRL6 (11% identical), FCGR1A (9% identical), FCRLB (8% identical), FCGR2B (8% identical), FCGR2A (7% identical), FCGR2C (7% identical), FCGR3A (7% identical), and 5 more.
Diseases named in the same sentence as PECAM1 in open-access papers:
PECAM1 is named in the same sentence as 604 diseases in open-access papers, as found by Europe PMC text mining. Sharing a sentence is not in itself a finding about the gene and the disease. The quoted sentences say what the papers report.
breast cancer (154 papers, 1997 to 2025). A primary or metastatic malignant neoplasm involving the breast. "Previous studies have shown that PECAM1 is associated with metastasis and progression of solid tumors, including gastric cancer, lung cancer, and glioma, melanoma and breast cancer." (PMID 29938007, 2018). "For example, one study found that tumour-associated endothelial cells (TECs) in breast cancer undergoing EndMT downregulated the endothelial-like marker PECAM1 and demonstrated enhanced migration and extracellular matrix remodeling capabilities compared to normal endothelial cells." (PMID 40083695, 2025). "Serum levels of both biomarkers, ICAM-1 and PECAM-1 were significantly higher in patients after breast cancer treatment and could be associated with cognitive dysfunction, depression, and vestibulocerebellar ataxia." (PMID 35366289, 2022). "The expression of PECAM1 has also been correlated with the proliferation and metastasis of melanoma and breast cancer cells." (PMID 40361912, 2025). "In breast cancer tissue, we observed that endothelial cells were located in the peripheral regions, consistent with the spatial expression pattern of the marker gene PECAM1." (PMID 38672453, 2024). "The obtained results, when compared to a group of healthy women, indicated a significant increase in ICAM-1 and PECAM-1 serum levels in patients after radical breast cancer treatment." (PMID 35366289, 2022). "In the current study, ICAM-1 and PECAM-1 serum levels were measured as potential biomarkers in 45 female patients in a long-term follow-up period after breast cancer treatment, and compared to 25 age-matched female healthy volunteers." (PMID 35366289, 2022). "Cell adhesion molecules such as ICAM, B1 integrin, P-selectin, PECAM-1, CXCL12 and SDF-1 have also been proposed as part of the mechanisms underlying breast carcinoma metastases." (PMID 36497364, 2022). "Binding to endothelium by adhesion molecules such as ICAM, B1 integrin, P-selectin, PECAM-1, CXCL12 and SDF-1 have also been proposed as part of the mechanisms underlying breast carcinoma metastases." (PMID 36497364, 2022). "Platelet endothelial cell adhesion molecule 1 (Pecam1) is an angiogenesis marker that has been suggested to assess the influence of microvessels and angiogenesis on the clinical outcome of breast cancer patients." (PMID 33742285, 2021). "In line with this, inhibition of PECAM-1 revealed a decrease in proliferation of murine melanoma and mammary carcinoma cells." (PMID 31344919, 2019). "High PECAM-1 expression has been found in human brain gliomas, carcinoma of the cervix, renal cell carcinoma, lung cancer and breast cancer." (PMID 31344919, 2019). "It is a member of the Immunoglobulin-superfamily PECAM-1 and it was reported that CD31 is involved in angiogenesis for example in early breast cancer." (PMID 29523110, 2018). "Consistent with the notion that tumors with higher ADAM8 levels are characterized by increased angiogenesis, a positive correlation was found between ADAM8 and CD31 (PECAM1) mRNA expression in tumor samples from patients with basal-like breast cancer." (PMID 24375628, 2014). "We also quantified the levels of VE-cadherin, PECAM-1 and vWF as an indicator of degree of angiogenesis in breast cancer, as we previously reported." (PMID 16430777, 2006). "Notably, PECAM1 overexpression has been shown to augment melanoma and breast cancer cell proliferation." (PMID 40361912, 2025). "In conclusion, our results provide a first hint that elevated serum levels of ICAM-1 and PECAM-1 could serve as early predictive biomarkers in breast cancer survivors that might help to improve the management of these patients." (PMID 35366289, 2022). "Furthermore, co-expression analysis by cBioPortal showed that BGN was positively associated with PECAM1 and ANGPT2 expression in human breast cancers." (PMID 33966638, 2021).
breast cancer (continued). "Indeed, PECAM1 has been detected on several rodent and human solid tumour cell lines, including breast carcinoma MCF7 and human brain glioblastoma." (PMID 29784888, 2018). "CD31 (PECAM1) is known to be a suitable marker for the identification of angiogenic blood vessels in many tissues, including breast cancer and is used as such in the pathological analysis of breast cancer." (PMID 23056178, 2012). "Cell adhesion molecules such as ICAM, B1 integrin, PECAM-1, P-selectin, CXCL12, and SDF-1 have also been proposed as part of the mechanism underlying breast carcinoma metastasis, and ICAM expression in meningiomas may also facilitate adhesion of metastases to meningioma blood vessels." (PMID 39099765, 2024). "In the group of patients following breast cancer treatment, the serum levels of ICAM-1 and PECAM-1 were 555 and 98 ng/mL, respectively." (PMID 35366289, 2022). "In an intergroup comparison, patients after breast cancer treatment showed a statistically significant increase in the level of ICAM-1 and PECAM-1 molecules." (PMID 35366289, 2022). "Pearson’s correlation coefficients showed that Biglycan mRNA expression was positively correlated with both PECAM1(Spearman’s correlation = 0.45) and ANGPT2 (Spearman’s correlation = 0.4) levels in human breast cancers." (PMID 33966638, 2021). "In contrast, the angiogenic markers PECAM1 and CD34 showed the highest mRNA expression in normal-like breast cancer." (PMID 34219652, 2021). "Moreover, >99% of the cells were negative for the epithelial cell adhesion molecule (EpCAM), a breast cancer epithelial cell surface marker; CD31, also known as platelet endothelial cell adhesion molecule (PECAM-1), an endothelial cell marker, and CD45, a pan-leukocyte marker." (PMID 22954256, 2012). "Moreover, an increase in the serum levels of biomarkers (i.e., ICAM-1, PECAM-1, NSE) and changes in functional connectivity together might indicate a complex lesion of the central nervous system in VAS in patients in the long-term period following breast cancer treatment." (PMID 37368372, 2023). "The analysis revealed a significant reliable increase in PECAM-1 and ICAM-1 molecules in patients following breast cancer treatment with depression in comparison to patients without depression." (PMID 35366289, 2022).
melanoma (144 papers, 2009 to 2026). A malignant, usually aggressive tumor composed of atypical, neoplastic melanocytes. "Whilst MCAM had previously been implicated in the interaction of melanoma cell‐derived EVs with endothelial cells, this represents, to our knowledge, the first description of an involvement of PECAM1 in EV uptake by endothelial cells." (PMID 39400522, 2024). "The newly generated brain-homing melanoma cell line YUMM1.1-BrM4 was used to reveal increased in vivo extravasation of melanoma cells across the BBB of barrier-compromised PECAM-1-deficient mice compared to controls." (PMID 37894438, 2023). "46% and 16% of Pecam1+ ECs were positive for both Pim3 and Bcl3 or Pim3 and Inhbb, respectively, indicating tumor-induced upregulation of the rCaps 6 h after melanoma injection." (PMID 39627185, 2024). "Analysis of B16-F10 metastatic mouse lungs by sorting PECAM1+ ECs, CellTracker+ melanoma and PECAM1-CellTracker- cell populations showed significantly higher levels of Pim3 in ECs, as compared to the other lung cell populations." (PMID 39627185, 2024). "The combined image analyses showed that the proportion of extravascular melanoma cells was significantly increased in PECAM-1-ko mice compared to PECAM-1-wt mice." (PMID 37894438, 2023). "Next, we assessed the effect of melanoma cells on PECAM-1 of the pMBMECs by adding melanoma cells to LifeAct-GFP+ pMBMECs cultures for one hour, followed by whole-cell protein lysis and western blot analysis." (PMID 37894438, 2023). "We reported significantly increased melanoma cell extravasation in PECAM-1-ko mice compared to PECAM-1-wt mice." (PMID 37894438, 2023). "We concluded that the pMBMECs’ PECAM-1 forms a target for the destruction of the endothelial cell junctions by melanoma cells during the intercalation process." (PMID 37894438, 2023). "Then, we examined the effect of inflammation- or PECAM-1-ko-compromised pMBMECs on melanoma cell adhesion and intercalation." (PMID 37894438, 2023). "Next, we applied in vitro live cell imaging to compare the intercalation of YUMM1.1-BrM4 melanoma cells into PECAM-1-wt or PECAM-1-ko LifeAct-GFP+ pMBMECs in multiple samples in parallel." (PMID 37894438, 2023). "Melanoma cells which over-express heparan sulfates can interact with endothelial cells by binding to PECAM-1." (PMID 34207884, 2021). "There is evidence that PECAM1/CD31 is involved in the progression of a variety of malignancies including melanoma and cancers of the lung and breast." (PMID 31850854, 2019). "It has also been reported that PECAM1+/VEGFR-2– subpopulation of melanoma cells induces VM in a PECAM1-dependent process." (PMID 28320399, 2017). "Finally, we challenged our in vitro results by an in vivo analysis of intra- versus extravascular melanoma cell localisation in the brains of PECAM-1-ko or PECAM-1-wild type (wt) mice." (PMID 37894438, 2023). "Using PECAM-1-ko mice for studying melanoma extravasation could raise the question about the role of PECAM-1 itself in this process." (PMID 37894438, 2023). "Also, YUMM1.1 and YUMM1.1-BrM4 melanoma cells adhered comparably to the apical surfaces of PECAM-1-ko or PECAM-1-wt pMBMECs, respectively." (PMID 37894438, 2023). "An in vivo study showed that an anti-PECAM-1 mAb inhibited metastasis in melanoma, and could be a potential target for CAR T cell therapy in metastatic melanoma." (PMID 34207884, 2021). "PECAM-1 has metastasis- and proliferation-promoting effects, which seem to be independent of tumor type, but have most clearly been shown in studies on late-stage melanoma progression." (PMID 31344919, 2019). "It was also confirmed that PECAM1+ melanoma cells are enriched and might lead to resistance during anti-VEGF therapy." (PMID 29560266, 2018). "Interestingly, PECAM 1 (CD31) expression was detected only in T-cadherin-positive clones suggesting the possible mechanism of “vascular mimicry” and compensatory reaction of melanoma cells to reduced expression of angiogenic factors." (PMID 26197340, 2015).
melanoma (continued). "Similarly, IgSF members such as L1CAM (CD171), NCAM (CD56), PECAM-1 (CD31), ALCAM (CD166), and ICAM-1 (CD54) have been associated with metastatic progression in a range of cancers including melanoma, glioma, breast, ovarian, endometrial, prostate, and colon cancer." (PMID 22272201, 2012). "An antibody against melanoma marker PMEL was used to detect the B16-F10 cells and Pecam1 probe to identify ECs." (PMID 39627185, 2024). "In this study, we first confirmed that cell surface expression of VCAM-1 and melanoma cell adhesion were comparable between PECAM-1-ko and PECAM-1-wt pMBMECs." (PMID 37894438, 2023). "Adhesion of B78chOVA melanoma cells was tested as shear-resistant arrest, yielding comparable values between PECAM-1-ko and PECAM-1-wt pMLuECs." (PMID 37894438, 2023). "Interleukin (IL)-1β stimulated pMBMECs or PECAM-1-knockout (-ko) pMBMECs were employed to model compromised BBB barrier properties in vitro and to determine increased melanoma cell intercalation compared to pMBMECs with intact junctions." (PMID 37894438, 2023). "Also, in the pMLuECs and B78chOVA melanoma cell system, we found increased intercalation of melanoma cells into PECAM-1-ko compared to PECAM-1-wt pMLuECs." (PMID 37894438, 2023). "Considering the increased intercalation of YUMM1.1-BrM4 melanoma cells into PECAM-1-ko pMBMECs in vitro, we asked whether YUMM1.1-BrM4 melanoma cells also showed increased extravasation across the BBB in PECAM-1-ko C57BL/6J mice in vivo." (PMID 37894438, 2023). "Finally, we also assessed YUMM1.1-BrM4 melanoma cell extravasation in the brains of PECAM-1-ko and PECAM-1-wt LifeAct-GFP+ mice." (PMID 37894438, 2023). "Given the evident impact of PECAM-1 absence in the pMBMECs on melanoma cell intercalation, we hypothesised that PECAM-1 might be a target of the melanoma cells during the disruption of the pMBMEC monolayer." (PMID 37894438, 2023). "Voura and colleagues have determined that in vitro, the extravasation process of human melanoma cells across human lung microvascular endothelial cells is independent of molecular interactions involving PECAM-1." (PMID 37894438, 2023). "Another study showed that PECAM1 (also known as CD31, a mediator of angiogenesis that regulates EC–cell interactions) positive melanoma cells have the ability to form tube-like structuresin vitro and could incorporate with vascular lumensin vivo." (PMID 29560266, 2018). "In vivo, one could argue about the effect of lack of PECAM-1 in platelets and the role of blood clot formation for melanoma cell extravasation." (PMID 37894438, 2023). "We observed that PECAM-1-positive vascular area in the tumours derived from the SK-amphiregulin cells was significantly larger than that in the tumours derived from SK-GFP cells, implying that amphiregulin expression in malignant melanoma enhanced angiogenesis." (PMID 30718742, 2019). "The PECAM-1-positive vascular area in the tumour tissue derived from the SK-IL13Rα2 cells was significantly larger when compared with the tumour derived from the SK-MEL-28 cells, implying that the expression of IL13Rα2 in malignant melanoma enhanced angiogenesis." (PMID 30718742, 2019). "Also, B78chOVA melanoma cell protein lysates were negative for any PECAM-1 signal." (PMID 37894438, 2023). "The non-immune cell clusters were made up of melanoma cells (MLANA, PMEL, MITF, DCT), endothelial cells (VWF, PECAM1) and fibroblast cells (COL1A1, COL3A1)." (PMID 36433984, 2022). "To ensure that it was indeed the melanoma cells expressing high levels of VEGFA and not endothelial cells of the blood vessels, we first evaluated the expression of VEGFA and an endothelial cell marker PECAM1 across all ROIs." (PMID 41168392, 2025).
angiosarcoma (111 papers, 2005 to 2026). A malignant tumor arising from the endothelial cells of the blood vessels. "For instance, in angiosarcoma, a rare type of cancer derived from the vasculature, inhibition of PECAM-1 raised YAP levels, but decreased the tubulogenic potential of the angiosarcoma cells." (PMID 33614496, 2020). "Recently, PECAM-1-low angiosarcoma cells have been shown to be more efficient in ROS detoxification than PECAM-1-high cells." (PMID 31344919, 2019).